BECN1 (beclin 1)
Diseases named in the same sentence as BECN1 in open-access papers (continued):
Sharing a sentence is not in itself a finding about the gene and the disease.
Obesity (31 papers, 2013 to 2026). Accumulation of substantial excess body fat. "Therapeutically, the expressions of both Cdkn2a and Becn1 are upregulated in obesity and positively associated with adiposity in mice and humans." (PMID 37169793, 2023). "As diet-induced obesity mice develop various metabolic disorders involving inflammatory adipose tissue, we examined the relationship between BECN1 and YAP expression in the iWAT of HFD-fed mice." (PMID 38744820, 2024). "Most remarkably, the p16INK4a, p14ARF, and BECN1 mRNA levels in subcutaneous adipose tissues of obese human individuals were significantly higher than that of non-obese individuals, linking p16INK4a, p14ARF, and BECN1 expression to obesity in human." (PMID 37169793, 2023). "While the previous studies help establish a strong relationship between miRNAs and Beclin 1 in obesity, their relationship to obesity-induced endothelial dysfunction requires further exploration." (PMID 32907629, 2020). "For example, berberine, a noted phytochemical, can decrease autophagy flux with the anti-obesity effect by destabilizing BECN1." (PMID 29882838, 2018). "The class III obesity (vs. normal/overweight) group was significantly associated with higher expression of CHK1 (log2-fold change = 1.4, p-value = 0.031) and Beclin 1 (log2-fold change = 0.6, p-value = 0.047) but lower expression of androgen receptor (AR; log2-fold-change = −0.8, p-value = 0.039)." (PMID 39766121, 2024). "We further investigated the correlation between Cdkn2a and Becn1 mRNA levels and obesity." (PMID 37169793, 2023). "Hence, blocking Cdkn2a-mediated BECN1 activity holds therapeutic potential to sustain beige adipocytes in treating obesity and related metabolic diseases." (PMID 37169793, 2023). "Collectively, our findings unveil insights into the molecular mechanisms by which Cdkn2a regulates beige adipocyte maintenance via BECN1-mediated autophagy and provide a potential therapeutic strategy to lock into a stable beige identity and treat obesity and related metabolic diseases." (PMID 37169793, 2023). "The discovery of new mechanisms for modifying BECN1 in adipocytes may provide novel therapeutic targets for obesity." (PMID 34085745, 2021). "Similarly, miR-376b, which is also found at high levels in subjects with obesity, targets Beclin 1 and induce autophagy impairment in different cell types." (PMID 32907629, 2020). "Our findings reveal that Cdkn2a and Becn1 function as potent positive regulators of beige-to-white adipocyte transition, providing a potential therapeutic target for pharmacological intervention to combat the obesity epidemic and its related metabolic diseases." (PMID 37169793, 2023). "Given that autophagy in the hypothalamus has been identified to regulate obesity, we then assessed the effect of EA on autophagy-related components LC3, p62, and Beclin-1." (PMID 36313328, 2022). "To investigate the effects of obesity and THC on autophagy, we measured the expression of the autophagy-related factors LC3, Beclin 1, and Atg5." (PMID 34222477, 2021). "Therefore, similar to our in vitro analysis, we evaluated FoxO induced autophagy markers Gabarapl1 and Beclin-1 in the obesity-induced mouse OA model treated with or without liposomal injections of adenosine or CGS21680." (PMID 33441836, 2021).
Cerebral ischemia (29 papers, 2012 to 2025). Restriction of arterial blood supply to the brain associated with insufficient oxygenation to support the metabolic requirements of the tissue. "Our results showed that 3-MA reduced the levels of Beclin-1 and MAPLC3β in cerebral ischemia and alleviated the behavioral abnormalities and neuronal damage caused by cerebral ischemia." (PMID 38397792, 2024). "In comparison with the Sham group, cerebral ischemia caused a notable upregulation in the expression of Beclin-1, Cathepsin B, and MAPLC3β." (PMID 38397792, 2024). "Collectively, our findings indicated that the neuroprotective effect of CAT against cerebral ischemia was associated with the inhibition of autophagy via the NRF1/KAT2A/METTL3/Beclin-1 axis." (PMID 38773376, 2024). "CAT activated the NRF1/KAT2A/METTL3 axis and downregulated Beclin-1 expression, thus relieving neuronal injury and excessive autophagy after cerebral ischemia." (PMID 38773376, 2024). "Taken together, CAT exerted the protective effect and autophagy regulation of cortical neuronal injury after cerebral ischemia via Beclin-1." (PMID 38773376, 2024). "TOM7 can modulate autophagy through the PINK1/Beclin 1 signaling after cerebral ischemia, and silencing TOM7 inhibits autophagy via the PINK1/Beclin 1 pathway to aggravate cerebral ischemia." (PMID 37856037, 2024). "Beclin-1 is regarded as a major regulator of autophagy, which playing a fatal role in human neurodegenerative diseases, including cerebral ischemia." (PMID 38773376, 2024). "SNHG14 promotes the expression of Atg5 and Beclin 1 by sponging miR-30b-5p, thereby activating autophagy and aggravating cerebral ischemia-reperfusion injury." (PMID 36275741, 2022). "The quantitative Western blot analyses of LC3, p62, and Beclin-1 demonstrate that autophagy was activated after global cerebral ischemia and peaked at 12 h." (PMID 29416039, 2018). "Both cerebral ischemia and ischemia-reperfusion can activate autophagy by inducing high expression of certain genes, including Becn1, LC3-II, and Atg5." (PMID 29088811, 2017). "Consistent with the previous study, we also found that the levels of LC3B and Beclin-1 were increased after cerebral ischemia." (PMID 27455253, 2016). "Beclin-1 positive cells increased in the ipsilateral hemisphere in a time-dependent manner after cerebral ischemia." (PMID 23688351, 2013). "To determine whether high levels of LC3B and Beclin-1 by Hcy treatment occur in a specific population of cells after cerebral ischemia, we co-stained for LC3B (or Beclin-1) and NeuN (neuron marker) (or glial fibrillary acidic protein (GFAP, astrocyte marker))." (PMID 27455253, 2016). "Furthermore, we showed that Hcy treatment enhanced the autophagy with the increased levels of LC3B and Beclin-1 protein after cerebral ischemia." (PMID 27455253, 2016). "Moreover, considering the adverse role of overactive autophagy in the process of stroke, we found that muscimol decreased the expression levels of Beclin-1, Cathepsin B, and MAPLC3β in cerebral ischemic rats, which suggested that muscimol inhibited autophagy induced by cerebral ischemia." (PMID 38397792, 2024). "Studies have found that autophagic cell death after cerebral ischemia is accompanied by an increase in Beclin 1 (a marker protein for autophagy) and LC-3; therefore, it can be inferred that neuronal death after cerebral ischemia may be related to overactivated autophagy." (PMID 36139821, 2022). "As a result, the present study revealed that CAT, the main active component of Rehmannia, protected against cerebral ischemia in vivo and in vitro by inhibiting neuronal injury and autophagy via the NRF1/KAT2A/METTL3/Beclin-1 axis." (PMID 38773376, 2024). "The levels of autophagy-related proteins, including Beclin-1, Atg3, Atg5, and LC3 in the hippocampus were effectively maintained and elevated at 28 days after cerebral ischemia/reperfusion in the young gerbils compared with those in the old gerbils." (PMID 35220404, 2022).
Cerebral ischemia (continued). "Autophagy can be activated after cerebral ischemia, and in our 2-VO tGCI model, autophagy was enhanced based on the temporal detection of LC3, Beclin-1, and p62 using Western blotting and the levels of LC3 using immunofluorescence." (PMID 29416039, 2018). "We found a dramatic elevation in Beclin-1 expression levels in both the DAHP treatment group and the TP treatment group challenged by cerebral ischemia." (PMID 25729215, 2015). "We and others have found that autophagy markers Beclin 1 and LC3-II were increased following cerebral ischemia." (PMID 22776356, 2012). "autophagy found in rats with cerebral ischemia could promote the expression of autophagy-related genes LC3-II and Beclin 1 in brain tissues, and decrease cerebral ischemia-reperfusion injury." (PMID 33819197, 2021). "Per our findings, ST2-104 peptide pretreatment further reversed MCAO or glutamate induced enhancement of Beclin-1 and LC3II expression, suggesting that the protective function of ST2-104 peptide has a close relationship with autophagy inhibition in cerebral ischemia injury." (PMID 34362425, 2021). "To determine the effect of GM1 on neuronal autophagic activities after MCAO, we first measured the LC3-II and Beclin-1 expression levels in brain tissue by immunostaining 72 hours after brain ischemia and quantified both the LC3-II and the Beclin-1 positive cells in the penumbra area." (PMID 26751695, 2016). "Accordingly, we analyzed the mechanism of CAT in cerebral ischemic via the NRF1/KAT2A/METTL3/Beclin-1 axis with the focus on neuronal injury and autophagy, aiming to offer a theoretical basis for the development of CAT as neuroprotective drugs for the prevention and treatment of cerebral ischemia." (PMID 38773376, 2024). "In summary, the present study demonstrated that an elevated Hcy level could enhance autophagy and aggravate neuronal cell injury following focal cerebral ischemia-reperfusion with the generation of autophagosomes and the upregulation of LC3B/Beclin-1 protein expression in neurons." (PMID 27455253, 2016). "Therefore, we examined whether selenium treatment affects the levels of Beclin 1 and LC3-II following focal cerebral ischemia." (PMID 22776356, 2012).
non-small cell lung carcinoma (29 papers, 2012 to 2025). A group of at least three distinct histological types of lung cancer, including non-small cell squamous cell carcinoma, adenocarcinoma, and large cell carcinoma. "XBS improves Bcl-2 and Beclin-1 communication, making it an effective treatment for gefitinib-resistant non-small cell lung cancer (NSCLC)." (PMID 39650649, 2024). "YBX1 promoted autophagy and decreased drug sensitivity of human non-small cell lung cancer cells by targeting p110β/Vps34/BECN1 pathway." (PMID 36642732, 2023). "Diminished levels of miR-216b have been detected in non-small cell lung cancer cells while enhanced miR-216b expression has been demonstrated to elevate cisplatin-induced apoptosis by targeting Beclin-1." (PMID 32972441, 2020). "EGFR activation by oncogenic mutations induces phosphorylation of BECN1 at Y229, Y233, and Y352, which suppress autophagy and enhance tumorigenesis in a NSCLC (non-small cell lung carcinoma) xenograft model." (PMID 30370269, 2018). "A recent study revealed that Beclin-1-mediated autophagy enhances the effectiveness of EGFR tyrosine kinase inhibitor (TKI) therapy in non-small cell lung carcinoma (NSCLC) cells." (PMID 29113343, 2017). "Herein, we employed immunohistochemistry (IHC) to detect the protein expression of Beclin 1 in non-small cell lung cancer (NSCLC) and paired normal adjacent lung tissues, and analyzed its clinicopathological/prognostic significance in NSCLC." (PMID 24260370, 2013). "However, the biological functions of BECN1 in non-small cell lung cancer (NSCLC) were obscure." (PMID 31272261, 2019). "This resulted in the downregulation of Beclin-1, β-catenin/TCF-4, and LC3II, leading to a reduction in the growth of cells and autophagy in non-small cell lung cancer (NSCLC)." (PMID 36899946, 2023). "Besides our research, another group has proved that active EGFR phosphorylated Beclin-1 to inhibit autophagy in non-small cell lung carcinoma (NSCLC) cells." (PMID 31378785, 2019). "Beclin-1 expression was inversely correlated with tumor size and primary tumor stage in human lung adenocarcinomas and was reduced in non-small cell lung carcinoma (NSCLC) relative to normal tissue." (PMID 25617802, 2015). "In non-small-cell lung cancer (NSCLC) cells like A549 and H1975, these designed peptides promoted autophagy and enhanced endolysosomal degradation of the over-expressed cell surface oncogenic receptor epidermal growth factor receptor (EGFR), two processes that are Beclin 1-dependent." (PMID 37598181, 2023). "PTEN regulates autophagy in PTEN/AKT/FOXO3a/ATG7 axis in non-small-cell lung cancer (NSCLC) cells, independent of mTOR and Beclin-1." (PMID 33344463, 2020). "In non-small cell lung cancer cell line models, GX15-070-induced Atg7-dependent autophagy independent of Beclin 1 and Bax/Bak." (PMID 22240779, 2012).
lymph node metastasis (27 papers, 2013 to 2024). "Beclin-1 expression was associated with lymph node metastasis and tumor grade, whereas Atg5 expression was associated with tumor grade, clinical stage, tumor size, and lymph node metastasis." (PMID 39650649, 2024). "In an independent study by Dong, it was observed that a decreased Beclin 1 expression was markedly linked to lymph node metastasis in intrahepatic cholangiocarcinoma, as well as to reduced overall survival and disease-free survival." (PMID 39664581, 2024). "In contrast, lack of beclin-1 expression in cancer cells with concomitant stromal beclin-1 expression was linked to local cancer recurrence and postoperative lymph node metastasis, and thus was significantly associated with a poor disease-free survival rate." (PMID 25955408, 2015). "In contrast, loss of beclin-1 in cancer cells and overexpression in stromal mesenchymal cells was associated with local cancer recurrence, postoperative lymph node metastasis, and a poor disease-free survival rate." (PMID 25955408, 2015). "For colorectal and esophageal squamous carcinoma, the significant associations between Beclin 1 level and vascular invasion as well as lymph node metastasis were observed." (PMID 24303007, 2013). "We found that negativity of Beclin 1 was associated with poor recurrence free survival, yet positivity of Beclin 2 was linked to poor prognostic factors, including positive lymphovascular status and lymph node metastasis." (PMID 26506105, 2015). "Interestingly, lack of beclin-1 expression in cancer cells and overexpression of beclin-1 in stromal cells tends to be associated with local recurrence and postoperative lymph node metastasis." (PMID 25955408, 2015). "Moreover, Beclin 1 downregulation was associated with lymph node metastasis and poor outcome in intrahepatic cholangiocellular carcinoma." (PMID 24303007, 2013). "Immunohistochemical staining revealed that a combination of loss of beclin-1 expression in cancer cells and overexpression of beclin-1 in cancer stromal mesenchymal cells was linked to local cancer recurrence and postoperative lymph node metastasis in invasive ductal carcinoma." (PMID 25955408, 2015). "It has been reported that autophagy-related Beclin-1 is overexpressed in cSCC lymph node metastasis." (PMID 35756488, 2022). "Multivariate Cox regression analysis showed that Beclin 1, EGFR, ALK mutations, tumor differentiation grade, TNM stage and lymph node metastasis were independently associated with PFS." (PMID 36401689, 2022). "Based on univariate analysis, a more advanced stage (p < 0.01), lymph node metastasis (p < 0.01), and low Beclin-1 expression (p < 0.01) were identified as prognostic factors correlated with poor OS." (PMID 34257544, 2021). "Expression of Beclin 1 and clinicopathologic characteristics (including age, histological grade, tumor size, lymph node metastasis status, AJCC stage and HER2 expression) were included in multivariate analysis." (PMID 28881721, 2017). "It is likely that continuous DDR2 expression, which is related to stromal beclin-1 expression, plays a role in local recurrence and lymph node metastasis." (PMID 25955408, 2015). "Cox’s regression analysis was performed using surgical stage, differentiation, pathological type, lymph-node metastasis, residual lesion size, and Beclin 1 expression as the dependent variables, and survival time as the independent variable." (PMID 24675697, 2014). "We further demonstrated that decreased expression of beclin-1 has been correlated with advanced clinical stage and T stage, poor differentiation, and lymph node metastasis." (PMID 23935917, 2013). "Combined with the finding in ICC, our data further demonstrated that the correlation between Beclin 1 low expression and lymph node metastasis was indeed existed both in ICC and ECC." (PMID 24303007, 2013). "We found that Beclin 1 was lowly expressed in cholangiocarcinoma, and correlated with lymph node metastasis." (PMID 24303007, 2013).
lymph node metastasis (continued). "In this study, we did not see the association of Beclin 1 with smoking, but high Beclin 1 appeared to be related to lymph node metastasis and high TNM stage." (PMID 36401689, 2022). "Furthermore, low expression of Beclin-1 was associated with more advanced ESCC stages and lymph node metastasis." (PMID 34257544, 2021). "Beclin-1 is poorly expressed in CC and is strongly correlated with lymph node metastasis." (PMID 34273969, 2021). "Moreover, the cholangiocarcinoma patients with lymph node metastasis (N1) had a lower Beclin 1 level than that of N0 subgroup (P=0.012)." (PMID 24303007, 2013). "However, studies in 2013 showed that Beclin 1 expression was significantly higher in papillary thyroid carcinoma and metastatic lymph nodes than in normal tissues, suggesting that the expression of Beclin-1 in papillary thyroid carcinoma is related to tumor occurrence and lymph node metastasis." (PMID 33055358, 2020). "Beclin-1 and LC3 expression were significantly correlated with T categories, differentiation and lymph node metastasis." (PMID 23935917, 2013). "Univariate analysis revealed that Beclin 1 level, EGFR and ALK mutations were associated with lymph node metastasis, TNM stage, tumor differentiation and prognosis, but not with gender, age and smoking status." (PMID 36401689, 2022). "Univariate analysis showed that Beclin 1 expression and EGFR and ALK mutations were associated with lymph node metastasis, TNM stage, tumor differentiation and prognosis, but not with gender, age and smoking status (P < 0.05)." (PMID 36401689, 2022). "In conclusion, our study confirmed that Beclin 1 low expression, a negative prognostic indicator, was correlated with lymph node metastasis for cholangiocarcinoma." (PMID 24303007, 2013).